PF4 (platelet factor 4)
Diseases named in the same sentence as PF4 in open-access papers (continued):
Sharing a sentence is not in itself a finding about the gene and the disease.
thrombosis (continued). "Specific ingredients in the vaccine trigger a strong anti-PF4 immune response, leading to thrombosis with thrombocytopenia syndrome." (PMID 37376503, 2023). "Protection against arterial thrombosis in Grin1fl/fl-Pf4-Cre+ mice suggests that the NMDAR is a potent therapeutic target for the prevention of arterial thrombosis in cardiovascular diseases such as acute myocardial infarction or abdominal aortic aneurysm." (PMID 37252113, 2023). "Among them, the most important and widely recognized function of PF4 is its participation in the formation of immune-related thrombosis." (PMID 36926331, 2023). "Treatment recommendations issued by The American Society of Hematology for VITT are similar to those for severe HIT in patients with low platelet count, thrombosis, and the positive detection PF4-heparin IgG as assessed by immunoassay." (PMID 38034388, 2023). "The presence of anti-PF4 antibody (sensitivity 97%, specificity 92% at our laboratory using enzyme-linked immunosorbent assay (ELISA)), high concentration of D-dimer and lower platelet count than on the 11th admission day might suggest that the patient had thrombosis with thrombocytopenia syndrome." (PMID 36355059, 2022). "PF4 interacted with the Fc-gamma receptor IIA (FcγRIIa) of platelets and then activated the platelets to enter a hypercoagulable state, leading to increased PF4 release and promoting arterial and venous thrombosis, which ultimately triggers VITT." (PMID 36419624, 2022). "The patients with thrombosis had high antibodies to platelet factor 4-polyanion complexes, which led to thrombosis via platelet activation." (PMID 36004026, 2022). "Here the authors show that anti-PF4 antibodies are responsible for the activation of platelets and neutrophils, and blockage of FcγRIIa or NETosis in vivo can prevent thrombosis." (PMID 36064843, 2022). "It appears that the mechanisms of TTS and HIT with thrombosis are quite similar in being mediated by PF4 antibodies, but clots in the brain are uncommon in HIT with thrombosis for reasons that are not clear." (PMID 34443589, 2021). "Recently, PF4 also has been associated with vector-based SARS-CoV-2 vaccine-induced thrombosis with thrombocytopenia syndrome (VITT/TTS), thus, emphasizing the clinical significance of PF4 in PF4/polyanion complex formation, and the occurrence of VITT/TTS." (PMID 34526009, 2021). "PF4 and P-selectin are released from activated platelets, PGVI is a platelet procoagulant mediator and elevated PAI-1 is a thrombosis risk factor." (PMID 33859620, 2021). "It has been reported in literature that antibodies specific for Platelet Factor 4 (PF4) were present at high levels in patients who presented thrombosis after vaccination with the AstraZeneca ChAdOx1 nCoV-19 vaccine." (PMID 34445266, 2021). "In recent reports, almost all the patients that presented post-COVID-19 vaccines thrombosis had high levels of antibodies to platelet factor 4 (PF4)–polyanion complexes identified by ELISA as well as other platelet-based activation assays." (PMID 34730750, 2021). "NETs can stimulate the production of anti-PF4 Abs and have pro-coagulant properties that can contribute to the development of thrombosis in HIT." (PMID 34557868, 2021). "On the basis of these evidences, we investigated the possible role of both Spike-RBD and PF4 proteins and their respective antibodies (Ab) in the etiopathogenesis of thrombosis in COVID-19 severe patients and in vaccinated people experiencing VITT." (PMID 34445266, 2021). "When PV patients with a positive history of thrombosis were assessed for anti-PF4 immune responses, we observed that 11.8% had anti-PF4/heparin IgG antibodies, as compared to 7.1% IgG positivity in PV patients who never had a thrombosis." (PMID 28698883, 2017). "Skin biopsies frequently show thrombosis in the dermal microvascular and biological tests (IgG class of anti-PF4/heparin antibodies, HIPA, and SRA) which are in favor of immune activation of platelets." (PMID 24307958, 2013).
thrombosis (continued). "The targeting of these PF4 complexes by immunoglobulin G (IgG) antibodies underlies anti‐PF4 disorders such as heparin‐induced thrombocytopenia (HIT) and Vaccine‐Induced Immune Thrombocytopenia and Thrombosis (VITT)/VITT‐like disorders." (PMID 40589323, 2025). "While some authors propose the simple approach, that anticoagulation should be continued for 3 months after normalization of the platelet count in VITT patients with thrombosis, others state that PF4 antibodies should disappear prior to discontinuation of anticoagulation." (PMID 39200920, 2024). "Thrombosis mediated by elevated anti-PF4/P autoantibodies may be one mechanism contributing to the clinical complications of CM." (PMID 38652559, 2024). "VITT has clinical and serological similarities to heparin-induced thrombocytopenia (thrombosis) (HIT(T)), an autoimmune disorder caused by autoantibodies against PF4 after exposure to heparin, which is also a polyanionic molecule that can form large complexes with PF4 in vitro." (PMID 38140254, 2023). "Thus, therapeutic strategies targeting PF4 and VWF-associated thrombosis are novel methods for the diagnosis and treatment of immune-associated thrombosis." (PMID 36926331, 2023). "In multivariable models, PF4 test positivity was associated with a higher risk of DVT (adjusted OR, 2.32 [95% CI, 1.81 to 2.95]), PE (adjusted OR, 2.75 [95% CI, 2.08 to 3.63]), and a composite of any thrombosis (adjusted OR, 1.86 [95% CI, 1.51 to 2.30])." (PMID 37907435, 2023). "Among them, PF4–VWF, as a new immune complex, may induce and promote the formation of immune-associated thrombosis and is expected to become a new target and therapeutic direction." (PMID 36926331, 2023). "A pathogenic Platelet Factor 4 (PF4)-dependent syndrome, unrelated to the use of heparin therapy, has been reported after the administration of vaccines in the patients manifesting acute thrombocytopenia and thrombosis." (PMID 34445266, 2021). "If TTS is suspected, urgent diagnostic workup should be arranged, including a complete blood count with a platelet count and peripheral blood smear, imaging for thrombosis based on signs/symptoms, PF4-ELISA (HIT assay) using blood drawn prior to any therapies and fibrinogen level." (PMID 34443589, 2021). "An underlying syndrome denoted “vaccine-induced immune thrombotic thrombocytopenia” (VITT) or “thrombosis with thrombocytopenia syndrome” (TTS) was described, consisting of thrombosis, thrombocytopenia and platelet-activating antibodies to platelet factor 4–polyanion complexes." (PMID 34930153, 2021). "The role of platelet factor 4 in vaccine-induced thrombosis with thrombocytopenia syndrome further reinforces the importance the platelet factor 4/polyanion immune complexes and the complications that this might pose to susceptible individuals." (PMID 34526009, 2021). "The fact that anti-PF4/heparin antibodies in PV patients with thrombosis were of IgG isotype may support a functional relevance of anti-PF4/heparin immune responses for increased thrombotic risk." (PMID 28698883, 2017). "A thrombogenic potential of anti-PF4/heparin IgM has not been clearly established and a causative implication for thrombosis in HIT remains on debate." (PMID 28698883, 2017). "This study demonstrated the presence of anti-β2-GPI/PF4 in patients with APS, where it may be involved in the mechanism underlying the hypercoagulable state and correlated with a greater risk of developing thrombosis, especially in the young population." (PMID 41601650, 2026). "We propose that this may be a potential mechanism of PF4/anti-PF4-mediated thrombosis." (PMID 41226302, 2025). "Furthermore, FJH-KO effectively attenuated carrageenan-induced plasma levels of β-TG and PF4, which are specific platelet alpha-granule proteins that are released upon platelet activation and are measured to evaluate platelet activation in a thrombosis model." (PMID 38139268, 2023).
thrombosis (continued). "The antibody-platelet factor 4/heparin complex may lead to platelet activation, accompanied by other cascading reactions, resulting in cerebral sinus thrombosis, deep vein thrombosis, lower limb arterial thrombosis, myocardial infarction, pulmonary embolism, skin necrosis, and thrombotic stroke." (PMID 34526009, 2021). "This article focuses on the central role of antibodies against platelet factor 4 (PF4) in mediating immunothrombosis, from classical heparin-induced thrombocytopenia (HIT) to vaccine-induced immune thrombocytopenia and thrombosis (VITT)." (PMID 41646984, 2026). "Anti‐platelet factor 4 (PF4) disorders include heparin‐induced thrombocytopenia (HIT) and vaccine‐induced immune thrombocytopenia and thrombosis (VITT)/VITT‐like disorders." (PMID 40589323, 2025). "It is known in HIT that vWF forms complexes with PF4, to which HIT antibodies bind and then activate neutrophils via their Fc part, exacerbating thrombosis." (PMID 37834770, 2023). "The plasma levels of β-thromboglobulin (β-TG), platelet factor 4 (PF4), and serotonin were measured to evaluate platelet activation in the carrageenan-induced thrombosis mouse model." (PMID 38139268, 2023). "Anti‐platelet factor 4 (PF4) antibodies that activate platelets via FcγRIIA drive the pathophysiology of vaccine‐induced immune thrombocytopenia and thrombosis (VITT)." (PMID 35515079, 2022). "The biomarkers for platelet activation may be a platelet factor 4 (PF4), β-thromboglobulin (β-TG), and P-selectin; however their actual diagnostic specificity for thrombosis due to platelet activation is not high, and they have limited use in the clinical laboratory." (PMID 34362190, 2021). "In APS, the onset of deep venous thrombosis appeared to be more frequent in patients who were positive for anti-β2-GPI/PF4 antibodies compared to those who were negative (p = 0.049)." (PMID 41601650, 2026). "Thrombosis with thrombocytopenia syndrome (TTS), which develops after administration of an adenovirus vector-based vaccine, is mediated by platelet-activating antibodies to platelet factor 4 (PF4)." (PMID 40710841, 2025). "According to initial studies, the prevalence of platelet-activating anti-PF4 antibodies might range between 1.5% and 3% in patients with monoclonal gammopathy of unknown significance (MGUS) and a history of thrombosis." (PMID 40236285, 2025). "PF4 suppresses ADAMTS13 (a disintegrin and metalloproteinase with a thrombospondin type 1 motif, member 13) activity when it binds to the VWF-A2 domain in a concentration-dependent manner, potentially worsening thrombosis." (PMID 36926331, 2023). "Vaccine-induced immune thrombocytopenia and thrombosis (VITT) are a rare but serious issue associated with SARS-CoV-2 mRNA vaccination, possibly mediated by anti-PF4 antibodies, which can be found after vaccination but not after COVID-19 infection." (PMID 37243082, 2023). "In several patients with thrombosis and TP following the AstraZeneca vaccine, high levels of PF4 antibodies were observed without history of heparin exposure." (PMID 34967105, 2022). "A previous study showed that, among 492 health care workers vaccinated with Vaxzevria, anti-PF4/polyanion antibodies without platelet-activating properties were found after vaccination in six individuals with normal platelet counts and no thrombosis." (PMID 35746602, 2022). "Our findings suggest that the ChAdOx1 nCov-19 vaccine can elicit anti-PF4 antibody production, even in recipients without a clinical manifestation of thrombosis." (PMID 34358129, 2021). "TTS should also be considered in the absence of signs, symptoms or imaging documenting thrombosis with a low platelet count and greatly increased or progressively increasing D-dimer counts or a positive PF4-ELISA test." (PMID 34443589, 2021).
thrombosis (continued). "Heparin-induced thrombocytopenia (HIT) is a relatively rare immune-mediated adverse reaction of heparin indicating by low platelet counts, as a result of anti-heparin-platelet factor 4 (PF4) antibodies, and arterial and venous thrombosis in almost 50–70% of patients with HIT." (PMID 33855053, 2021). "Autoimmune anti-PF4/heparin antibodies developed in HIT activate platelets and may ultimately lead to arterial or venous thrombosis." (PMID 33306320, 2020). "Overall, 45% of PV patients experienced thromboses with 11.8% positive for anti-PF4/heparin IgG versus 7.1% in PV without thrombosis." (PMID 28698883, 2017). "However, in patients with severe anti-PF4 thrombosis or those requiring intensive care, DOACs are not recommended." (PMID 40236285, 2025). "However, the mere presence of PF4 antibodies need not necessarily imply thrombosis in either HIT or VITT." (PMID 35246163, 2022). "The presence of anti-PF4 antibodies was not sufficient to provoke clinically evident thrombosis." (PMID 34358129, 2021). "If low platelet count would be present (it could also be mild initially), a chest and abdominal CT scan should be performed to rule out venous thrombosis, together with an anti-PF4/heparin IgG enzyme immunoassay and functional platelet assay." (PMID 34341358, 2021). "It is unclear whether the ChAdOx1 nCov-19 vaccine can induce the development of anti-PF4 antibodies in vaccinated individuals who have not developed thrombosis." (PMID 34358129, 2021). "D-Dimer levels usually drop sharply during anticoagulation of deep vein thrombosis, and the sustained increase seen in our series may point towards a prolonged prothrombotic condition that may or may not be related to the presence of anti-PF4 antibodies." (PMID 36016324, 2022). "Furthermore, it is unclear whether the vaccine can induce the development of anti-PF4 antibodies (seroconversion) in vaccinated individuals who have not developed thrombosis, since the data published so far are limited to patients with overt thrombotic complications." (PMID 34358129, 2021). "Secreted platelet factor 4 (PF4 or CXCL4) may serve as a biomarker for VTE in humans, although its direct involvement in venous thrombosis pathophysiology is not exactly known." (PMID 36361963, 2022).
atherosclerosis (67 papers, 2010 to 2026). A disease characterized by the build-up of fatty material and calcium deposition in the arterial wall resulting in partial or complete occlusion of the arterial lumen. "PF4 has been implicated in the pathogenesis of several chronic inflammatory disorders, including atherosclerosis and neurodegenerative diseases." (PMID 39558855, 2025). "For example, M4 macrophages, induced by platelet factor 4 (CXCL4), exhibit both pro-inflammatory and foam cell-like properties and have been implicated in atherosclerosis." (PMID 40076729, 2025). "Platelet factor 4 is a pleiotropic inflammatory chemokine that has been implicated in various inflammatory disorders, including atherosclerosis." (PMID 35300669, 2022). "Acceleration of atherosclerosis and the regulation of megakaryopoiesis have also been linked to PF4, as well as the activation of leukocytes, including monocytes, neutrophils and NK cells." (PMID 27631372, 2016). "The generation of both PF4 deficient mice (PF4-/-) on a B6 background and mice overexpressing human PF4 has shed light to its central role in thrombus formation and atherosclerosis." (PMID 22792197, 2012). "Importantly, PF4 has already been associated with atherosclerosis development and could represent another biomarker of atherosclerosis and possibly of valve remodeling." (PMID 35295264, 2022). "Therefore, it needs to be investigated in depth whether PF-4var, showing physico-chemical and biological properties different from PF-4, can affect atherosclerosis and why reduced levels of PF-4var are associated with a poor outcome in CAD patients." (PMID 22384011, 2012). "Since the PF4 expression of macrophages and PF4-induced macrophages were pivotal to atherosclerosis via multiple mechanisms, including inflammation activation, they warrant further investigation in the context of hypoxia-induced RV remodeling." (PMID 41281604, 2026). "In vivo murine experiments also demonstrated that injection of activated platelets exacerbated atherosclerosis by P-selectin-dependent deposition of PF-4 and RANTES." (PMID 41302081, 2025). "We now report that, in the present atherosclerosis inflammation resolution study, there is also a cluster of macrophages in the plaques of IgG control mice that is enriched in Pf4." (PMID 41066197, 2025). "Several mediators of platelet activation are involved in the initiation of plaque growth (e.g., CD62P) and can intensify the inflammation and thus progression of atherosclerosis (e.g., PF-4)." (PMID 41002634, 2025). "Secretion of platelet chemokine PF4 from activated platelets in atherosclerosis models promotes further macrophage differentiation." (PMID 36831393, 2023). "Platelet factor 4 has been shown to be involved in various inflammatory responses, including vascular inflammation and atherosclerosis." (PMID 35300669, 2022). "Platelet factor 4 promotes vascular inflammation by recruiting monocytes to adhere to damaged endothelial cells in atherosclerosis." (PMID 35300669, 2022). "Immunostaining results of anti-CD41 or anti-PF4 showed the presence of platelets in atherosclerosis plaques, which is consistent with our original findings." (PMID 34815786, 2021). "For example, heterodimerization of CCL5 with CXCL4 (platelet factor 4) has a synergetic effect on monocyte adhesion, whereas disruption of this heterodimer attenuates atherosclerosis development." (PMID 32817341, 2020). "The PF4- RANTES heterodimers have been proposed to represent potential therapeutic targets in the treatment of atherosclerosis." (PMID 23372649, 2013). "Increased PF4 levels are observed in inflammatory or infectious disease, diabetes, cardiovascular and renal disease, atherosclerosis and other conditions affecting vascular health or in response to traumatic medical procedures or cardiopulmonary bypass." (PMID 23561460, 2013).